LSM8 (LSM8 homolog, U6 small nuclear RNA associated)
Description:
Plays a role in pre-mRNA splicing as component of the U4/U6-U5 tri-snRNP complex that is involved in spliceosome assembly, and as component of the precatalytic spliceosome (spliceosome B complex). The heptameric LSM2-8 complex binds specifically to the 3'-terminal U-tract of U6 snRNA.
Synonyms: YJR022W
Tractability: Small molecule: a structure with a bound ligand is known. PROTAC: ubiquitination databases record sites on it; its protein half-life has been measured.
Gene: Protein-coding gene on chromosome 7 (118,183,976 to 118,204,035, forward strand). Ensembl gene ENSG00000128534.
Subcellular location: Nucleus
Subcellular location (Human Protein Atlas): Nucleoplasm; Vesicles
Pathways (Reactome):
Metabolism of RNA: mRNA Splicing - Major Pathway
Gene Ontology:
Molecular function: protein binding; RNA binding; mRNA binding; U6 snRNA binding
Biological process: mRNA splicing, via spliceosome; spliceosomal snRNP assembly; spliceosomal tri-snRNP complex assembly
Cellular component: Lsm2-8 complex; nucleus; precatalytic spliceosome; spliceosomal complex; U2-type precatalytic spliceosome; U4/U6 x U5 tri-snRNP complex; nucleoplasm; U4/U6 snRNP; U4atac/U6atac snRNP; U4atac/U6atac x U5 tri-snRNP complex; U6 snRNP; U6atac snRNP
Genetic constraint (gnomAD): Loss-of-function variants: 13 observed, 14.53 expected, observed/expected ratio (o/e) 0.89, 90% interval 0.58 to 1.42. The upper end of that interval is the gene's LOEUF score, 1.42, which puts it in group 5 of 6, group 1 being the genes least tolerant of losing a copy. Missense variants: 81 observed, 108.49 expected, observed/expected ratio (o/e) 0.75, 90% interval 0.62 to 0.9. Synonymous variants: 49 observed, 40.47 expected, observed/expected ratio (o/e) 1.21, 90% interval 0.96 to 1.54.
Homologues: Orthologues: guinea pig LSM8 (100% identical), macaque LSM8 (100% identical), mouse Lsm8 (100% identical), rabbit LSM8 (100% identical), rat Lsm8 (100% identical), tropical clawed frog lsm8 (96% identical), zebrafish lsm8 (91% identical), dog LSM8 (90% identical), pig LSM8 (79% identical), chimpanzee LSM8 (77% identical), Drosophila melanogaster CG2021 (68% identical), Caenorhabditis elegans lsm-8 (56% identical). Paralogues in human: LSM1 (34% identical).
Diseases named in the same sentence as LSM8 in open-access papers:
LSM8 is named in the same sentence as 10 diseases in open-access papers, as found by Europe PMC text mining. Sharing a sentence is not in itself a finding about the gene and the disease. The quoted sentences say what the papers report.
depression (2 papers, 2021 to 2024). "In addition, rs263575 [BNC2/CNTLN] had a marginally significant indirect effect on broad depression among females but not males, and rs2402273 [LSM8/CTTNBP2] had a marginally significant indirect effect on broad depression among males but not females." (PMID 38790194, 2024).
cutaneous melanoma (1 paper, 2022). A primary melanoma arising from atypical melanocytes in the skin. "LSM8 was weakly expressed in cutaneous melanoma and normal tissues." (PMID 36371223, 2022).
malignant thyroid tumors (1 paper, 2022). "Interestingly, the roles of top-ranked discriminatory proteins such as SNRPB2, PRPF3, and LSM8 in other diseases have been investigated for years, although there is limited evidence about the associations between these molecules and malignant thyroid tumors." (PMID 35923625, 2022).
tumor (2 papers, 2022 to 2023). "In this study, we have firstly identified LSM5 and LSM8 as favourable biomarkers related to 5-FU chemotherapy resistance and investigated their relationship with tumor microenvironment and immune therapy in GC patients." (PMID 37007092, 2023). "In this study, Tcm infiltration was positively correlated with LSM8 and LSM12 but negatively correlated with LSM2 and LSM4, which was consistent with the effect of genes on tumor prognosis." (PMID 36371223, 2022). "Additionally, with the analysis of tumor immunity and chemoresistance, we were the first to demonstrate that LSM5 and LSM8 were tightly correlated with chemoresistance and immune infiltration, and thus might be potential biomarkers for predictions of survival in GC patients." (PMID 37007092, 2023).
cancer (1 paper, 2008). A tumor composed of atypical neoplastic, often pleomorphic cells that invade other tissues. "Some of these genes were found to be expressed in increased levels in certain cancers (Hnrpd and Lsm8), including highly invasive types." (PMID 18706093, 2008).
LSM8 also shares sentences with these, for which no sentence is quoted: breast carcinoma (2 papers); Anxiety (1); colorectal cancer (1); lung carcinoma (1); mesothelioma (1).